SF1 (splicing factor 1)
Diseases named in the same sentence as SF1 in open-access papers (continued):
Sharing a sentence is not in itself a finding about the gene and the disease.
pituitary tumor (4 papers, 2019 to 2024). A benign or malignant neoplasm affecting the pituitary gland. "Clinically, INHBA agonists can promote the INHBA-ACVR1B pathway to eliminate SF1 lineage pituitary tumors or increase the infiltration of CX3CR1+ macrophages in other lineages, helping PitNET treatment." (PMID 38658971, 2024). "We demonstrated that the LHRH responders had a higher frequency of pituitary tumors positive for SF-1, GnRHR, and LH." (PMID 38954291, 2024). "Therefore, pituitary tumors in LHRH responders of acromegaly might express steroidogenic factor 1 (SF-1), a gonadotroph transcription factor, as the phenotype of gonadotroph in addition to pituitary-specific positive transcription factor 1 (PIT-1) as that of somatotroph." (PMID 38954291, 2024). "Results from previous molecular profiling of GH-secreting pituitary tumors showed their 3, clinically relevant molecular subtypes: DG PIT1/SF1, DG PIT1, and SG PIT1 tumors." (PMID 39497133, 2024). "According to the 2022 WHO classification of pituitary tumors, somatotroph tumors and gonadotroph tumors express PIT-1 and SF-1, respectively." (PMID 38954291, 2024).
somatotroph tumors (4 papers, 2022 to 2025). "Several studies have reported concurrent PIT1 and SF1 immunopositivity in unusual PitNETs, which otherwise reflected somatotroph tumors." (PMID 38228887, 2024). "According to classification of PitNETs, SF-1 is a well-established marker of gonadotroph tumors and the observation that it is also expressed in a particular subtype of somatotroph tumors may suggest a need of slight revision of classification criteria." (PMID 36497102, 2022). "SF-1 (NR5A1) is a commonly accepted marker of pituitary gonadotroph cell lineage; therefore, its higher expression in group 1 of somatotropinomas requires special attention." (PMID 36497102, 2022). "Thus, the frequency of PIT1/SF1 co-expression among PitNETs, which do not fit into the WHO class of somatotroph tumors has yet to be determined." (PMID 38228887, 2024).
adrenal hyperplasia (3 papers, 2016 to 2022).
Azoospermia (3 papers, 2019 to 2025). Absence of any measurable level of sperm,whereby spermatozoa cannot be observed even after centrifugation of the semen pellet. "Patients carrying multiple variants consistently exhibited more severe phenotypes, particularly the triad of micropenis, testicular hypotrophy, and azoospermia, illustrating additive or synergistic disruption of SF-1 function." (PMID 41386844, 2025). "A novel heterozygous missense variant, c.584C > T (p.Ser195Phe), located in the hinge region of SF-1, was identified in three unrelated individuals presenting with micropenis, testicular hypotrophy, and azoospermia." (PMID 41386844, 2025).
breast carcinoma (3 papers, 2007 to 2023). "The top three genes for breast cancer tissues and cell lines were SF1 + TRA2B + THRAP3 and THRAP3 + RHOA + QRICH1, respectively, and therefore a total of 5 RGs (SF1, TRA2B, THRAP3, RHOA, QRICH1) should be considered." (PMID 34895237, 2021). "There was a high correlation (R2 from 0.815 to 0.979 in breast cancer tissues, and R2 from 0.927 to 0.995 in breast cancer cell lines) between stable RGs and SF1 + TRA2B + THRAP3 + RHOA + QRICH1." (PMID 34895237, 2021). "There was also a moderate-to-high correlation (R2 from 0.621 to 0.709 in breast cancer tissues, and R2 from 0.600 to 0.916 in breast cancer cell lines) between unstable RGs and SF1 + TRA2B + THRAP3 + RHOA + QRICH1." (PMID 34895237, 2021). "We found, that SF1 was the most stably expressed gene according to geNorm and ComprFinder but ranked fifth by NormFinder and fourth by BestKeeper and the ΔCt method in breast cancer tissue samples." (PMID 34895237, 2021). "In the breast cancer tissue group, the three most stably expressed genes (with the lowest M values) were SF1, THRAP3, and TARDBP, while GAPDH, DNAJC8, and B2M were the least stably expressed genes." (PMID 34895237, 2021). "Therefore, we considered the multi-RG combination SF1 + TRA2B + THRAP3 + RHOA + QRICH1 as the most promising choice for breast cancer research (both in breast cancer tissues and cell lines)." (PMID 34895237, 2021). "Therefore, to confirm the roles of these genes on the vital regulatory mechanisms in breast cancer, we compared the potential role of novel RGs (SF1, TRA2B, THRAP3, RHOA, and QRICH1) vs. traditional RGs (ACTB, and GAPDH) in the normalization of target gene expression." (PMID 34895237, 2021). "Our results show that RG combinations SF1 + TRA2B + THRAP3 and THRAP3 + RHOA + QRICH1 showed stable expression in breast cancer tissues and cell lines, respectively, and that they displayed good interchangeability." (PMID 34895237, 2021). "In breast cancer cell lines, when the optimal RG combinations SF1 + TRA2B + THRAP3 + RHOA + QRICH1, SF1 + TRA2B + THRAP3, or THRAP3 + RHOA + QRICH1 were used for normalization, the expression of FAAH was highest in MCF-7 cells, followed by MCF-10A cells, and was least in MDA-MB-231 cells." (PMID 34895237, 2021). "Our results indicated that SF1, TRA2B, and THRAP3 were the top 3 stably expressed RGs in breast cancer tissues and that THRAP3, RHOA, and QRICH1 were the top 3 stably expressed RGs in breast cancer cell lines." (PMID 34895237, 2021). "Therefore, we recommend that SF1 + TRA2B + THRAP3 and THRAP3 + RHOA + QRICH1 be adopted as the RG combinations for breast cancer tissue and cell line research, respectively." (PMID 34895237, 2021). "The bound structure of receptors with ligands is considered a therapeutic target for breast cancer treatment and we have docked the native ligand as well, to check how our proposed compound advances and found that ziprasidone has better binding affinities which are shown in the ST2 and SF1." (PMID 37783782, 2023).
corticotroph adenomas (3 papers, 2022 to 2025). "This analysis revealed regulon patterns characteristic for the major PitNETs histological subtypes, with distinct TF activity signatures in PIT-1 linage tumors, SF-1–positive gonadotropinomas, and TPIT–positive corticotropinomas." (PMID 40813692, 2025).
diabetes (3 papers, 2021 to 2025). "The CELF2-related AS events of NECTIN2, DYRK1B, SF1 and FN1 were significantly different and may be potential therapeutic targets for diabetes-related vascular disease." (PMID 40692719, 2025). "We conducted a comparative analysis of age, sex, education, BMI, history of hypertension and diabetes, and blood lipids among PitNETs patients and healthy controls, I-PitNETs and NI-PitNETs patients, F-PitNETs and NF-PitNETs, and PIT1 and SF-1 lineage PitNETs patients." (PMID 41470032, 2025).
IMAGe syndrome (3 papers, 2020 to 2022). IMAGe syndrome is characterized by the association of intrauterine growth retardation, metaphyseal dysplasia (and short limbs), adrenal hypoplasia congenita, and genital anomalies. "As one of the components of IMAGe syndrome, and unlike its conventional presentation, AHC of IMAGe syndrome is not caused by a DAX1 nor an SF-1 mutation." (PMID 34948037, 2021).
ovarian carcinoma (3 papers, 2013 to 2022). A malignant neoplasm originating from the surface ovarian epithelium. "This indicated a potential for the development of a new ovarian cancer treatment through SF-1 inducing angiogenesis." (PMID 26576867, 2015). "Therefore, impairment of WT1-transcriptional activity may pose a risk factor for the development of testicular and ovarian cancer through the dysregulation of DAX1 and SF1 proteins." (PMID 35610319, 2022). "Steroidogenic factor-1 (SF-1), the product of the NR5A1 gene, is an essential transcription factor that is known to regulate steroidogenesis in ovarian epithelia, including the synthesis of progesterone, a suppressor of ovarian cancer." (PMID 23291911, 2013). "In addition, they noted that SF-1 protein expression is not significantly different between benign and malignant ovarian tumors." (PMID 26576867, 2015). "We have previously shown that while human SF-1 and StAR are expressed in normal OSE cells, ovarian cancer cell lines SKOV-3, OVCar3 and BG1 do not show SF-1 or StAR expression." (PMID 23291911, 2013).
ovarian dysfunction (3 papers, 2011 to 2021). The inability of the ovaries to function. "Other genes like the WNT4, ESR2 and SF-1 have a necessary role for ovarian and testicular development function as demonstrated by the fact that genetic variants in these genes cause gonadal dysgenesis in 46,XY individuals, with ovarian failure in women and ovotesticular DSD42,70,74." (PMID 31745224, 2019). "Although more studies are needed to understand the natural history of these changes in more detail, and to establish how prevalent or predictable ovarian dysfunction might be, these cases do highlight that SF-1 plays a role in human ovarian function too." (PMID 21078366, 2011).
pancreatic cancer (3 papers, 2015 to 2022). "A two-stage case-control study was conducted to examine the association between six candidate U2-depedent spliceosome genes (SRSF1, SRSF2, SF3A1, SF3B1, SF1 and PRPF40B) and pancreatic cancer (PC)." (PMID 26498691, 2015).
adrenal carcinoma (2 papers, 2013 to 2023). A carcinoma involving a adrenal gland. "Importantly, 1/8 aging Sf1-Rspo1GOF females had a well-differentiated adrenal carcinoma with capsular invasion." (PMID 37102205, 2023).
cervical cancer (2 papers, 2016 to 2023). A primary or metastatic malignant neoplasm involving the cervix. "Both PITX1 and SF-1 interact and bind to and promote expression in the hCYP11B1 promoter region in the cervical cancer cell line HeLa." (PMID 37841446, 2023). "Overexpression of BORIS sf6 in cervical cancer cells increased sphere formation and tumor-initiating ability compared with those in control cells, whereas overexpression of BORIS sf1 and BORIS sf4 resulted in only slight increases." (PMID 26849232, 2016).
colon cancer (2 papers, 2020 to 2025). "SF1 is implicated in the regulation of Wnt signaling in colon cancer cells, particularly in the SW480 cell line." (PMID 40754247, 2025). "In comparison, very high levels of SF1 were detected in the HT-29 human colon cancer cell line." (PMID 33202710, 2020).
gastric cancer (2 papers, 2022 to 2023). A primary or metastatic malignant neoplasm involving the stomach. "Some of these markers have been identified for their potential functions in cancer: FDX1 can be activated by SF1 and cJUN in Leydig cells, CDKN2a usually functions as a tumor suppressor in many cancers, and DLAT has also been reported to be an oncogene in gastric cancer." (PMID 37190215, 2023).
glioma (2 papers, 2011 to 2021). A benign or malignant brain and spinal cord tumor that arises from glial cells (astrocytes, oligodendrocytes, ependymal cells). "We found an overexpression of DLGAP5, NEK2, and PBK, while the expression of SF1, PTEN, ATRX, and DAXX was downregulated in tumor tissues as compared to normal tissues of the patients with glioma." (PMID 35095717, 2021). "On the other hand, 10 genes showed 0- to 2-fold decrease, 6 genes showed 2- to 10-fold decrease and RORβ, SF1 and PNR showed more than 10-fold decrease in BTSCs compared with glioma." (PMID 21224854, 2011).
HIV-1 infection (2 papers, 2009 to 2012). The type species of lentivirus and the etiologic agent of acquired immunodeficiency syndrome (AIDS). "Therefore, any growth disadvantage associated with Tat-SF1 suppression may be outweighed in vivo by a selective advantage in the context of an HIV-1 infection." (PMID 23153325, 2012). "Upon Tat-SF1 depletion, the level of HIV-1 infection decreased approximately 3-fold compared to the control cells." (PMID 19479034, 2009). "Thus, whilst this study reveals that Tat-SF1 functions as an HDF in SupT1 cells, further studies are required to determine whether variants might modulate HIV-1 infection and its suppression would have a long-term inhibitory effect on HIV-1 replication in vivo." (PMID 23153325, 2012).
Hypertension (2 papers, 2024 to 2025). The presence of chronic increased pressure in the systemic arterial system. "We don’t know.”Mother, SF1, T6, SDHB variant in her and her daughter, leading to the discovery of hypertension in the mother)." (PMID 38802530, 2024).
hypogonadism (2 papers, 2017 to 2025). A disorder characterized by decreased function of the gonads. "A male with a de novo heterozygous NR5A1/SF-1 variant (c.937C > T, p.Arg313Cys) (index case 14) presented with severely undervirilised external genitalia and hypogonadism at birth." (PMID 40037090, 2025). "NR5A1 (also named SF1) encoding the steroidogenic factor 1 is not only important for the formation of bipotential gonads and sex determination, but also involved in the pathogenesis of hypogonadism in mice." (PMID 28295047, 2017).
leiomyosarcoma (2 papers, 2015 to 2023). An uncommon, aggressive malignant smooth muscle neoplasm, usually occurring in post-menopausal women. "Both SF-1 and CYP19A1 genes were expressed in the tumor, and expression levels of these genes were markedly higher in the tumor than in uterine leiomyosarcoma." (PMID 26576867, 2015).
Leydig cell tumor (2 papers, 2023 to 2025). A sex cord-stromal tumor occurring in the testis and rarely in the ovary. "Although we have not found any published cases of normal adult OLC expressing SF1 immunopositivity, up to 55% of Sertoli–Leydig cell tumors are reported to be SF1 positive." (PMID 40220034, 2025). "In this context, SF1 expression may be misleading in the differential diagnosis with other steroidogenic tissues and tumors, such as steroidogenic gonadal neoplasms (e.g., steroid cell tumor, Leydig cell tumor)." (PMID 37166678, 2023).
lung carcinoma (2 papers, 2022 to 2025). "In lung cancer, the splicing factor QKI represses the inclusion of NUMB alternative exon through competing with a core splicing factor SF1, thereby inhibiting proliferation and Notch signaling." (PMID 36304260, 2022). "In PM2.5-induced lung cancer, circCDR1as specifically binds to splicing factor 1 rich in serine/arginine (SRSF1), affecting SRSF1's splicing of VEGFA mRNA and ultimately inhibiting lung cancer cell apoptosis, thereby promoting the development of PM2.5-induced lung cancer." (PMID 40290118, 2025).
neuroblastoma (2 papers, 2014 to 2020). Neuroblastoma (NB) is the most common solid, extracranial childhood tumor. "In the neuroblastoma cell line Neuro2A, Celf3 formed novel nuclear bodies (named CS bodies) that colocalized with SF1, another Gomafu-binding protein." (PMID 25145264, 2014). "Interestingly, Celf3 formed novel nuclear bodies (CS bodies) in the neuroblastoma cell line Neuro2A that colocalized with SF1, another Gomafu-interacting protein." (PMID 25145264, 2014). "Interestingly, SF-1 has also been mentioned in association with MYCN and neuroblastoma progression." (PMID 33396509, 2020).
pituitary carcinoma (2 papers, 2017 to 2020). A primary or metastatic malignant neoplasm affecting the pituitary gland. "Pit-1 will be immunoreactive in pituitary carcinomas of the somatotroph, lactotroph, and thyrotroph lineages while SF1 and GATA3 will be immunoreactive in the carcinomas of the gonadotroph lineage." (PMID 32622369, 2020). "SF1 immunostaining was helpful to identify the tissue origin of the metastatic deposit and to confirm the pituitary carcinoma." (PMID 28284009, 2017). "A biopsy of the foramen magnum lesion, demonstrating cells with vacuolated, clear cytoplasm and positive SF1 staining confirmed a pituitary carcinoma, for which she was commenced on temozolomide chemotherapy." (PMID 28284009, 2017).
primary adrenal insufficiency (2 papers, 2011 to 2024). A hormonal disorder that occurs when the adrenal glands fail to release adequate amounts of glucocorticoids (cortisol), mineralocorticoids (aldosterone, 11-deoxycorticosterone), and androgens (dehydroepiandrosterone) to meet physiologic needs, despite release of ACTH from the pituitary. "Thus, it appeared that SF-1 could be a cause of primary adrenal insufficiency in 46,XX girls." (PMID 21078366, 2011). "Although primary adrenal insufficiency associated with variants in SF-1/NR5A1 was not common, human gonad (and especially testis) development and function seemed much more sensitive to the effects of reduced SF-1 function." (PMID 38281359, 2024).
sex cord-stromal tumor (2 papers, 2023 to 2025). A neoplasm involving a sex cord. "Because of inhibin and SF-1 positivity and the nesting, these tumors have been designated as sex cord tumors." (PMID 37097347, 2023). "SF-1 and inhibin are known to be the most sensitive for GCTs, but SF-1 is also known to stain positively in all sex-cord stromal tumors, and some GCTs can be completely negative for inhibin on IHC." (PMID 40438800, 2025).
X-linked adrenal hypoplasia congenita (2 papers, 2016 to 2021). A X-linked condition characterized by underdevelopment of the adrenal gland and adrenal insufficiency caused by mutation(s) in the NR0B1 gene, resulting in decreased activity of the nuclear receptor protein DAX1, which may be associated with hypogonadotropic hypogonadism. "Non-CAH comprised 9.6% (n = 18) of the total patients whose etiologies included SF-1 gene mutation (n = 1), X-linked adrenal hypoplasia congenita (n = 9), aldosterone synthase deficiency (ASD, n = 4), and pseudo-hypoaldosteronism type 1 (PHA1, n = 1)." (PMID 34243750, 2021).
allergic rhinitis (1 paper, 2023). Inflammation of the nasal mucous membranes caused by an IgE-mediated response to external allergens. "To determine the effects of SF1 in a murine allergic rhinitis model, we examined the reactivity of SF1 to HEVs in NALTs using immunofluorescence." (PMID 37735247, 2023). "Since SF1 significantly blocks lymphocyte homing and allergic rhinitis in mice, future studies using SF1 will advance our understanding of the role of 6-sulfo sLex in health and disease." (PMID 37735247, 2023).
amenorrhea (1 paper, 2010). The absence of menses in a woman who has achieved reproductive age. "Among the genetic causes of low-testosterone primary amenorrhea due to 46,XY DSD, SRY gene is reported to be frequently involved, but other genes, such as SF1 and WT1, have never been studied for their prevalence." (PMID 20302644, 2010).
anorchia (1 paper, 2011). "In a study of a cohort of 24 boys with bilateral anorchia (vanishing testis syndrome) in France, one individual was found to carry a heterozygous SF-1 mutation (p.V355M)." (PMID 21078366, 2011).
Anorexia (1 paper, 2016). Lack of desire to eat (loss of appetite). "The intact anorexia presumably account for remaining body weight reductions observed in OVX+E SF1-p110α-KO mice." (PMID 26988598, 2016).
asplenia (1 paper, 2018). "Sf1 has also been implicated in murine spleen development, and in 2014 and 2016, asplenia and/or hyposplenia was reported in some individuals with SF1 mutations with undetermined functional consequences." (PMID 29769693, 2018).
benign ovarian tumors (1 paper, 2022). "In this setting, some benign ovarian tumors such as fibroma/fibrothecoma also enter the differential diagnosis; SF-1 and inhibin, in addition to c-KIT and DOG-1, can be used to differentiate these lesions." (PMID 35885469, 2022).
breast tumor (1 paper, 2021). "In the breast tumor tissue group, the 3 most stably expressed RGs were SF1, TRA2B, and THRAP3." (PMID 34895237, 2021).
chronic myelogenous leukemia (1 paper, 2010). "Moreover, BORIS sf1 was found to be expressed in many types of primary cancers, including retinoblastoma, chronic myelogenous leukemia, and mucoepidermoid carcinoma." (PMID 21079786, 2010).